SPP1 (secreted phosphoprotein 1)
Diseases named in the same sentence as SPP1 in open-access papers (continued):
Sharing a sentence is not in itself a finding about the gene and the disease.
autoimmune disease (62 papers, 2010 to 2026). A disorder resulting from loss of function or tissue destruction of an organ or multiple organs, arising from humoral or cellular immune responses of the individual to their own tissue constituents. "Numerous studies have demonstrated that OPN encoded by the secreted phosphoprotein 1 (SPP1) gene is associated with the pathogenesis and progression of some autoimmune diseases." (PMID 38256074, 2024). "The present study found that several genes encoding histocompatibility antigens were highly expressed in Leydig cells and T cells, and several genes associated with autoimmune disease were also abnormally expressed in testis of db/db mice, such as Ctla2a, Ccl7, and Spp1." (PMID 38817616, 2024). "Advances in understanding specific SPP1 SNiPs may be helpful to create genetic profiles for predisposition to autoimmune diseases, including IgAN." (PMID 31159229, 2019). "In tumor diseases, SPP1 can activate PI3K/AKT and FAK pathways, drive epithelial mesenchymal transition, induce MDSC proliferation, and inhibit CD8 + T cell activity; in autoimmune diseases, SPP1 leads to local inflammatory cell infiltration." (PMID 41384115, 2025). "SPP1 is a pro-inflammatory molecule that plays a crucial role in autoimmune diseases by regulating Th17 cells." (PMID 38915395, 2024). "SPP1 is a pro-inflammatory molecule and plays an essential role in autoimmune disease by regulating Th17 cells." (PMID 36008770, 2022). "Numerous studies demonstrated that OPN encoded by secreted phosphoprotein 1 (SPP1) gene, as well as polymorphism of the SPP1 gene, are associated with the pathogenesis and progression of some autoimmune diseases." (PMID 31159229, 2019). "Recently, the upregulation of SPP1 has been revealed in various autoimmune diseases [including systemic lupus erythematosus], inflammatory diseases [including Crohn’s disease and multiple sclerosis (MS)], and neurodegenerative diseases (NDDs) such as Alzheimer’s disease (AD)." (PMID 38259505, 2023). "In previous studies, SPP1 has been found to play significant roles in diverse biological processes such as biomineralization, bone remodeling, and immunological process, and is correlated with multiple diseases such as autoimmune diseases, osteoarthritis, and inflammatory diseases." (PMID 35593388, 2022).
osteoporosis (61 papers, 2011 to 2025). A condition of reduced bone mass, with decreased cortical thickness and a decrease in the number and size of the trabeculae of cancellous bone (but normal chemical composition), resulting in increased fracture incidence. "High expression of SPP1 is a risk factor for osteoporosis, as it positively regulates osteoclasts and inhibits bone mineral deposition." (PMID 39590301, 2024). "Few epidemiologic studies have explored the association between SPP1 polymorphisms and osteoporosis or BMD." (PMID 24831687, 2014). "A recent meta-analysis found that secreted phosphoprotein-1 (SPP1) can predict the risk of both osteoporosis and fracture." (PMID 24831687, 2014). "Because SPP1 is involved in osteogenesis and bone remodeling, SPP1 polymorphisms may play an important role in the pathogenesis of osteoporosis." (PMID 24831687, 2014). "Abnormal SPP1 expression is associated with a variety of skeletal disorders, and clinical studies have shown that serum SPP1 levels are positively correlated with the severity of osteoporosis and can be used as a biomarker for the early diagnosis of osteoporosis in postmenopausal women." (PMID 41357134, 2025). "Several large GWAS have investigated the genetics of osteoporosis, revealing BMD-associated genes, including ESR1, LRP4, ITGA1, LRP5, SOST, SPP1, TNFRSF11A (RANK), TNFRSF11 (RANKL), and TNFRSF11B (OPG)." (PMID 39769358, 2024). "As IRX2 is strongly expression in human primary osteoblasts of the skeleton, its putative roles in SPP1 regulation in osteoarthritis and osteoporosis are worthy of investigation." (PMID 28105936, 2016). "SPP1 genetic markers may be important for the prediction of osteoporosis at an early age." (PMID 24831687, 2014). "SPP1 signalling and COL1A1 signalling in osteoporosis were previously reported; and NT5E, HTRA1 and ANGPT1 signalling pathways reported here require further confirmation." (PMID 27690016, 2016). "Ectopic expression of circ‐SLC8A1 promoted ALP, BGLAP, SPP1 and BMP4 expression and silenced circ‐SLC8A1 inhibited ALP, BGLAP, SPP1 and BMP4 expression, and it suggested that circ‐SLC8A1 acted as promotive role in the development of osteoporosis." (PMID 34490735, 2021). "Secreted phosphoprotein 1 (SPP1), collagen type I α 1 chain (COL1A1), 5′-nucleotidase ecto (NT5E), HtrA serine peptidase 1 (HTRA1) and angiopoietin 1 (ANGPT1) and their signalling pathways are shown to be involved in osteoporosis in CD patients." (PMID 27690016, 2016). "Elevated SPP1, COL1A1 and NT5E proteins may be secreted from the pituitary tumor to directly target the skeletal system, with resultant osteoporosis, while downregulated HTRA1 and ANGPT1 may deregulate in bone formation and development." (PMID 27690016, 2016). "SPP1 (secreted phosphoprotein 1), COL1A1 (collagen type I α 1 chain), NT5E (5′-nucleotidase ecto), HTRA1 (HtrA serine peptidase 1) and ANGPT1 (angiopoietin 1) and their signalling pathways involving osteoporosis in CD patients are identified." (PMID 27690016, 2016). "In addition, these studies did not assess the association between SPP1 genetic polymorphisms and low BMD or osteoporosis." (PMID 24831687, 2014).
COVID-19 (60 papers, 2020 to 2026). A disease caused by infection with severe acute respiratory syndrome coronavirus 2. "Spp1 expression is an emerging biomarker in various diseases, with the presence of Spp1+ macrophages being linked to poor prognosis in severe COVID-19, active TB infection, lung fibrotic diseases, and cancer (42, –, 51)." (PMID 40704794, 2025). "High plasma levels of SPP1 were unique to severe COVID-19 when compared with other causes of severe pneumonia, and IHC localized SPP1+ macrophages in the alveoli of COVID-19 lung." (PMID 34143756, 2021). "They identified neutrophils (IFITM2, IFITM1, H3-H3B, SAT1 and S100A8) and macrophage cluster-1 (CCL8, CCL3, CCL2, KLF6 and SPP1) as the main immune cell subsets associated with severe COVID-19 cases." (PMID 34109284, 2021). "Among the identified gene signatures, IFITM2, IFITM1, H3F3B, SAT1, and S100A8 gene signatures were highly associated with neutrophils, while CCL8, CCL3, CCL2, KLF6, and SPP1 were associated with macrophage cluster-1 in severe-COVID-19 patients." (PMID 33138195, 2020). "In addition to ILDs, SPP1 has been implicated in infectious granulomatous lung diseases, lung and pleural malignancies, airway diseases, and COVID-19." (PMID 40559389, 2025). "Macrophages from patients with IPF and COVID-19 were both found to express fibrosis-associated genes including Secreted Phosphoprotein 1 (SPP1), transforming growth factor beta 1 (TGFB1), transforming growth factor beta-induced (TGFBI), legumain (LGMN), and C-C Motif Chemokine Ligand 18 (CCL18)." (PMID 37759460, 2023). "In summary, this study suggests that the pathogenesis of acute severe COVID-19 pneumonitis and RA synovitis might be driven by similar pathogenic myeloid cell clusters/pathways, producing SPP1 that persists into post-COVID-19 syndrome." (PMID 34143756, 2021). "To validate the computational scRNAseq findings of shared pathogenic macrophage clusters in COVID-19 and RA, we quantified plasma concentrations of their key shared functional mediators SPP1 (osteopontin) and S100A12 (calgranulin C) in a cross-sectional comparison of additional patient groups." (PMID 34143756, 2021). "High plasma SPP1 is associated with a severe disease trajectory of COVID-19." (PMID 34143756, 2021). "ScRNA-seq analyses of BAL and autopsy lung tissue from patients with severe COVID-19 have revealed a marked increase in SPP1 expression, particularly in macrophages." (PMID 40559389, 2025). "Previous studies provided a spatially resolved atlas of COVID-19 alveolar damage, identifying macrophage-derived SPP1/osteopontin signaling as a key regulator of early pro-inflammatory and pro-fibrotic pathways." (PMID 41222876, 2025). "In COVID-19 cases, it has been observed that macrophage SPP1 drives the differentiation of PD-L1high neutrophils, which are considered hallmarks of severe COVID-19." (PMID 38355515, 2024). "Single-cell transcriptome analysis found that SPP1 was significantly higher in bronchoalveolar lavage in severe cases of COVID-19 compared to control and mild cases." (PMID 38167532, 2024). "In contrast to acute severe COVID-19 where proinflammatory monocytes and profibrotic SPP1, LGMN expressing macrophages have been reported to be abundant, monocytes represented a minor constituent of PCLD BAL." (PMID 38827740, 2024). "Nasal macrophages had several differentially expressed (DE) genes in patients with COVID-19 versus patients with LRTD that mirrored alveolar macrophage responses (SPP1, LGALS1 and TMSB10), including IFN-γ response genes (HLA-DPB1, HLA-DQA1 and C1QB)." (PMID 39567718, 2024). "We noticed histone H1.5 is, with SPP1, the first protein to increase in fatal COVID-19 (TG4-F, death after >28 days)." (PMID 38787940, 2024). "More importantly, MAFB knockdown led to a significant downregulation of the gene sets that define the pathogenic SPP1+ MØ (GSE145926), MoAM3 (GSE155249), or CD163+/LGMN+ MØ (accession number EGAS00001005634) subsets in severe COVID-19." (PMID 37917179, 2023).
COVID-19 (continued). "For example, profibrotic SPP1+ monocyte-derived macrophages (MDMs) have previously been reported in COVID-19, IPF and cancer." (PMID 37291214, 2023). "In contrast, IL1B and IL18 transcripts were expressed in the SPP1/MERTK+ (inflammatory monocyte-derived) macrophage cluster in the COVID-19-infected samples." (PMID 37737611, 2023). "This link between SPP1 and neutrophils is supported by the correlation between plasma SPP1 and the blood neutrophils/lymphocytes ratio in our COVID-19 cohort." (PMID 34143756, 2021). "Of prognostic importance for COVID-19 patients, higher levels of SPP1 and S100A12 at the time of hospital admission and before antiinflammatory treatment were predictive of urgency for subsequent Intensive Care Unit (ICU) transfer." (PMID 34143756, 2021). "In line, a subset of alternative M2 macrophages expressing especially profibrotic genes (TREM2, TGFB1, and SPP1) was also identified in patients with severe COVID-19." (PMID 33604758, 2021). "The increased number of SPP1+ macrophages and upregulation of SPP1 plasma levels were selective for severe COVID-19." (PMID 34143756, 2021). "SPP1 was unaffected by age in SARS-CoV-2– pneumonia but was higher in COVID-19 patients > 70 years old, suggesting that SPP1 levels are related more to severity of pneumonia than age." (PMID 34143756, 2021). "SPP1 protein is expressed by COVID-19 BALF macrophages, drives proinflammatory activation of classical monocytes, and the differentiation of neutrophils toward a proinflammatory CD274+ (PD-L1+) phenotype." (PMID 34143756, 2021). "To investigate the biological effects of SPP1, we stimulated healthy whole blood cells with SPP1 at concentrations equivalent to those in severe and post–COVID-19 (200 and 50 ng/mL, respectively)." (PMID 34143756, 2021). "Macrophages with FABP4, known as the alveolar macrophages, were reduced while macrophages with FCN1 and SPP1, considered as the monocyte-derived proinflammatory macrophages, were strikingly increased in COVID-19 patients." (PMID 33762651, 2021). "SPP1 and CD68 staining of postmortem lung tissue confirmed abundant clusters of SPP1+ macrophages in alveoli of COVID-19 patients (n = 2), while it was rare in normal lung (n = 3) and sparse in alveoli of bacterial (n = 3) and H1N1 (n = 3) pneumonia." (PMID 34143756, 2021). "The macrophage cluster-1-derived signature (CCL8, CCL3, CCL2, KLF6, and SPP1) was confirmed to be significantly higher in severe cases of COVID-19 compared to control and mild cases." (PMID 33138195, 2020). "FABP4 was preferentially expressed in healthy controls and in patients with moderate COVID-19, while FCN1 and SPP1 were expressed in patients with severe COVID-19." (PMID 32612615, 2020). "This review will focus on the role of SPP1 in the pathogenesis of various acute and chronic lung diseases, including interstitial lung diseases (ILDs), granulomatous lung diseases, lung malignancies, airway diseases, pulmonary hypertension, and COVID-19." (PMID 40559389, 2025). "Additionally, increased SPP1 protein levels in BALF were found to be a predictive marker for post–COVID-19 interstitial lung disease." (PMID 40608428, 2025). "In addition, BAL alveolar macrophages from severe/critical COVID-19 patients showed an increased surface expression of several markers, such as ficolin-1 and secreted phosphoprotein 1 (SPP1)." (PMID 36941580, 2023). "Like SPP1, CXCL10, and CCL2, whose plasma levels associate with COVID-19 severity, the plasma level of CCL18 was also found to be significantly different between patients with mild and critical COVID-19." (PMID 37917179, 2023). "Recent human COVID-19 autopsy and transplant lung studies identified abundant interstitial pro-fibrotic monocyte-derived macrophages characterized by increased expression of SPP1, MMP9, and CTSZ." (PMID 35857635, 2022).
COVID-19 (continued). "Next, we investigated whether concomitant pharmacological drug treatment, demographic factors (age and sex), and COVID-19 comorbidities contributed to the plasma levels of SPP1, S100A12, GAS6, and PROS1." (PMID 34143756, 2021). "High plasma SPP1 selective for severe COVID-19 suggested a role for SPP1 in pathogenesis." (PMID 34143756, 2021). "Interestingly, levels of SPP1 were uniquely higher in those with severe COVID-19 compared with any other groups, including severe pneumonia induced by other pathogens." (PMID 34143756, 2021). "This suggests that a sustained raised level of SPP1 may contribute to post–COVID-19 pathologies and may influence future responses against pathogens by skewing monocytes toward proinflammatory phenotype." (PMID 34143756, 2021). "Indeed, BAL fluid SPP1 levels are predictive of post-COVID-19 ILDs, and profibrotic monocyte-derived alveolar macrophages, which are SPP1hi, are expanded in patients suffering from post-acute sequelae of COVID-19 (PASC) with persistent respiratory symptoms." (PMID 40559389, 2025). "In addition, the control group for the key mediator SPP1 in severe COVID-19 was the non–SARS-CoV-2 pneumonia group that matched COVID-19 for age, and it showed lower levels of SPP1 compared with COVID-19, supporting the link between SPP1 and COVID-19 pathogenesis." (PMID 34143756, 2021). "These transcriptomic profiles suggest that BALF FCN+ and FCN+SPP1+ macrophage clusters predominant in severe COVID-19 shared pathogenic molecular pathways, including the expression of their signature mediators S100A12 and SPP1 with ST CD48hiS100A12+ and CD48+SPP1+ clusters predominant in active RA." (PMID 34143756, 2021). "In summary, COVID-19 pneumonitis appears driven by similar pathogenic myeloid cell pathways as those in RA, and their mediators such as SPP1 might be an upstream activator of the aberrant innate response in severe COVID-19 and predictive of disease trajectory including post–COVID-19 pathology." (PMID 34143756, 2021). "Previously, we showed that the proinflammatory subtype of monocytes (Mon IFI30) accompanies severe Delta COVID-19, and this population yields high expression of IFI30, C15orf48, CXCL8, CSTB, and SPP1 genes." (PMID 39712003, 2024). "We next tested different combinations of the 4 cytokines for the prediction of disease death and found that the combination of SPP1, CCL18m and CXCL10 best discriminated between survival and death of patients with COVID-19 (AUC of 0.86)." (PMID 37917179, 2023). "In human COVID-19, expression of IL1B and IL18 shifted from mostly alveolar macrophages to SPP1/MERTK+ macrophages." (PMID 37737611, 2023). "Macrophages: Macrophages involved in COVID-19, are primarily inflammatory monocyte-derived, which express FABP4, ficolin-1 (FCN1), and SPP1 in case of mild and severe disease respectively." (PMID 35002519, 2022). "The shared key pathogenic macrophages were SPP1+ and S100A12+ clusters, and their signature SPP1 and S100A12 mediators were confirmed in COVID-19 cross-sectional and longitudinal patient plasma samples." (PMID 34143756, 2021). "Several AD markers (CXCL10, TNFRSF1B, SPP1, TGFB1, GSTM3, and NKTR) have significantly altered expression in COVID-19 patients." (PMID 34108016, 2021). "We investigated the persistence of increased plasma SPP1, S100A12, GAS6, and PROS1 into the SARS-CoV-2– post–COVID-19 phase, often characterized by complex pathologies." (PMID 34143756, 2021). "The BALF FCN1+ and FCN1+SPP1+ macrophage clusters from severe COVID-19 patients shared transcriptomic profiles with STM CD48hiS100A12+ and CD48+SPP1+ clusters from active RA, respectively." (PMID 34143756, 2021). "Plasma concentrations of SPP1 and S100A12 (key products of macrophage clusters shared with active RA) were high in severe COVID-19 and predicted the need for Intensive Care Unit transfer, and they remained high in the post–COVID-19 stage." (PMID 34143756, 2021).